ZNF32 (zinc finger protein 32)
Description:
May be involved in transcriptional regulation.
Synonyms: KOX30; ZNF637; Zfp637
Tractability: PROTAC: ubiquitination databases record sites on it; its protein half-life has been measured.
Gene: Protein-coding gene on chromosome 10 (43,643,859 to 43,649,367, reverse strand). Ensembl gene ENSG00000169740.
Subcellular location: Nucleus
Subcellular location (Human Protein Atlas): Nuclear bodies; Nucleoplasm; Cytosol
Gene Ontology:
Molecular function: protein binding; sequence-specific double-stranded DNA binding; DNA-binding transcription factor activity, RNA polymerase II-specific; RNA polymerase II cis-regulatory region sequence-specific DNA binding
Biological process: regulation of transcription by RNA polymerase II
Cellular component: nucleus
Genetic constraint (gnomAD): Loss-of-function variants: 13 observed, 25.7 expected, observed/expected ratio (o/e) 0.51, 90% interval 0.33 to 0.8. The upper end of that interval is the gene's LOEUF score, 0.8, which puts it in group 3 of 6, group 1 being the genes least tolerant of losing a copy. Missense variants: 239 observed, 343.48 expected, observed/expected ratio (o/e) 0.7, 90% interval 0.62 to 0.77. Synonymous variants: 115 observed, 125.06 expected, observed/expected ratio (o/e) 0.92, 90% interval 0.79 to 1.07.
Homologues: Orthologues: chimpanzee ZNF32 (100% identical), macaque ZNF32 (99% identical), dog ZNF32 (99% identical), pig ZNF32 (99% identical), rabbit ZNF32 (98% identical), rat Zfp637 (96% identical), mouse Zfp637 (95% identical), zebrafish si:zfos-932h1.3 (36% identical). Paralogues in human: ZNF585B (43% identical), ZNF157 (42% identical), ZNF175 (42% identical), ZNF229 (42% identical), ZNF568 (42% identical), ZNF717 (42% identical), ZNF182 (42% identical), ZNF26 (42% identical), ZNF30 (42% identical), ZNF300 (42% identical), ZNF37A (42% identical), ZNF7 (42% identical), and 164 more.
Diseases named in the same sentence as ZNF32 in open-access papers:
ZNF32 is named in the same sentence as 12 diseases in open-access papers, as found by Europe PMC text mining. Sharing a sentence is not in itself a finding about the gene and the disease. The quoted sentences say what the papers report.
breast carcinoma (4 papers, 2015 to 2025). "The present study deepens the understanding of ZNF32 mutations with respect to nuclear speckle formation and their roles in the proliferation of breast cancer cells." (PMID 40046230, 2025). "In the present study, we successfully induced ZNF32 histidine 179 and 183 double-site (H179, 183A) and single-site (H179A, H183A) mutations in breast cancer cell lines and observed the appearance of NSs in the cells." (PMID 40046230, 2025). "In conclusion, the ZNF32/GPER/ERK axis was positively associated with breast cancer development in vivo." (PMID 30478301, 2018). "For further analyse the significance of GPER in breast cancer stem-like cell populations caused by ZNF32 overexpression, we evaluated their role in Taxol-associated cell viability." (PMID 30478301, 2018). "Here, we innovatively show the effect of ZNF32 on cell autophagy and autophagy-associated cell death in breast carcinoma cells and also elucidate its underlying mechanisms." (PMID 25786368, 2015). "H2O2- and diamide-induced MCF-7 cell death models were used to elucidate the role of ZNF32-associated autophagy in breast carcinoma cell death." (PMID 25786368, 2015). "Studies have shown that histidine 179A and 183A (H179, 183A) of the ZNF32 protein exhibit point-like nuclear speckles, but the causes of such speckle formation and their effects on breast cancer cells remain unknown." (PMID 40046230, 2025). "In vivo and in vitro experiments were conducted to confirm that ZNF32 histidine 179 and 183 single-site mutations (H179A, H183A) but not double-site mutation (H179, 183A) could promote the proliferation of breast cancer cells." (PMID 40046230, 2025). "Consequently, we aimed to investigate the effect of ZNF32 on breast cancer autophagy and viability and elucidate the underlying molecular mechanisms." (PMID 25786368, 2015). "All of the results indicated that ZNF32 is associated with breast cancer autophagy." (PMID 25786368, 2015). "Both single-site and double-site mutations of ZNF32 could form NSs, but the single-site mutations promote proliferation of breast cancer cells by up-down-regulating the expressions of specific genes while the double-site mutation does not affect cell proliferation." (PMID 40046230, 2025). "Thus, the different zinc finger structure mutations of ZNF32 show inconsistent formation of NS-like structures and may also have different effects on the proliferation of breast cancer cells." (PMID 40046230, 2025). "ZNF32 may protect breast cancer cells from excessive autophagy-associated cell death." (PMID 25786368, 2015). "In this study, we prepared breast cancer cells containing ZNF32 H179, 183A, H179A, and H183A and observed nuclear speckles in all three cell types." (PMID 40046230, 2025). "This study deepens the understanding of the functions of ZNF32 mutants and NSs in breast cancer cells while providing a basis for exploring novel treatments for breast cancer." (PMID 40046230, 2025). "The in vivo and in vitro experiments showed that ZNF32 H179A and H183A promote proliferation of breast cancer cells." (PMID 40046230, 2025). "Based on the results of the combined transcriptome and metabolome sequencing analyses, we explored the effects of ZNF32 H179A, H183A, and H179, 183A on breast cancer cells." (PMID 40046230, 2025). "Together, ZNF32 H179A and H183A promote the proliferation of breast cancer cells by differentially upregulating ISY1-RAB43 and UPK3BL1 as well as downregulating SNX22 expressions." (PMID 40046230, 2025). "The enhanced expression of ZNF32 contributes to tumour formation and tumour growth in breast cancer xenografts." (PMID 30478301, 2018). "Taken together, GPER expression was shown to be critical for the stem cell-like properties of breast cancer cells induced by ZNF32 over-expression." (PMID 30478301, 2018).
breast carcinoma (continued). "Then, we took advantage of a series of molecular biology and bioinformatic methods to further investigate the mechanisms of ZNF32 regulation of the stem cell-like properties of breast cancer cells." (PMID 30478301, 2018). "We then analysed publicly available patient datasets, found that elevated ZNF32 and GPER expression was significantly associated with a higher risk of death in patients with breast cancer." (PMID 30478301, 2018). "Limiting dilution assays were used to further study the effects of ZNF32 on breast cancer stem cell frequency." (PMID 30478301, 2018). "To examine the clinical relevance of ZNF32 and GPER expression in breast cancers, we measured the expression of GPER and ALDH1 in ZNF32-high or ZNF32-low expression breast cancer samples using IHC." (PMID 30478301, 2018). "Zinc finger protein 32 (ZNF32), a newly discovered transcription factor, has been reported to be associated with breast cancer progression." (PMID 30478301, 2018). "In the present study, we examined the relationship between ZNF32 and GPER, a membrane-associated estrogen receptor, and we addressed their roles in stemness regulation in human breast cancer cell lines." (PMID 30478301, 2018). "We also evaluated the impact of ZNF32/GPER in the regulation of breast cancer stem cell-like properties during tumour formation and tumour growth in mouse models." (PMID 30478301, 2018). "GPER mediates the stem cell-like properties of breast cancer cells induced by ZNF32, as demonstrated by our silencing experiment." (PMID 30478301, 2018). "Taken together, these results suggest that GPER, along with the ERK signal transduction pathway, mediates the breast cancer stem cell-like properties induced by ZNF32." (PMID 30478301, 2018). "GPER expression was shown to be positively correlated with breast cancer stem cell-like properties and that ZNF32 regulates GPER expression." (PMID 30478301, 2018). "We then analysed the expression of ZNF32 and the stem cell marker Nanog in breast cancer cells from a database (Cancer Cell Line Encyclopedia, CCLE)." (PMID 30478301, 2018). "We provide novel insights into the regulation and function of GPER induced by ZNF32 in breast cancer cells." (PMID 30478301, 2018). "In conclusion, these findings indicate that ZNF32 effectively decreases the autophagosome number and influences the autophagic process in breast carcinoma cells." (PMID 25786368, 2015). "Surprisingly, we found that ZNF32 expression was positively correlated with LC3 II expression in breast cancer patients (R = 0.807)." (PMID 25786368, 2015). "To better understand the relationship between ZNF32 and autophagy, we collected breast cancer samples from 49 cases and used western blot analysis to detect the ZNF32 and LC3 II expression levels." (PMID 25786368, 2015). "In conclusion, ZNF32 acts as an effective autophagy inhibitor to protect breast cancer cells from excessive stimulus-autophagy-induced cell death." (PMID 25786368, 2015). "Most unpredictably, we observed a positive correlation between ZNF32 and autophagy in breast cancer patients, which was inconsistent with our observations in vitro and in the mouse models." (PMID 25786368, 2015). "Together, these indicate that ZNF32 NS formation maybe related to the transcriptional activity of RNA polymerase II and growth factor activity and that these may affect the growth of breast cancer cells." (PMID 40046230, 2025). "ZNF32 H179A, H183A, and H179, 183A differentially regulate breast cancer cell proliferation in vivo and in vitro, and we explored whether the single-site mutations could regulate proliferation through specific regulation of the downstream gene expressions." (PMID 40046230, 2025). "In addition, we verified that ZNF32/GPER regulates breast cancer stem cell-like properties in breast cancer tissues of patients." (PMID 30478301, 2018). "Consequently, in this study, we studied the effects of ZNF32 on breast cancer stem cell populations." (PMID 30478301, 2018).
breast carcinoma (continued). "ZNF32 could also modulate autophagy and protect breast cancer cells from stimulus-induced cell death." (PMID 30478301, 2018). "Considering these results, it was reasonable to hypothesize that ZNF32 could serve as a gene for enhanced stemness in breast cancer cells." (PMID 30478301, 2018). "Considering that stem-like cells have a greater ability to form mammospheres, we hypothesized that ZNF32 expression may play a role in breast cancer stem cell-like properties." (PMID 30478301, 2018). "The percentage of ALDH1-positive cells increased in ZNF32 over-expressing cells and decreased in ZNF32 knockdown cells could also be observed in these two additional breast cancer cell lines, MCF-7 and MDA-MB-231." (PMID 30478301, 2018). "Furthermore, we also analyzed the correlations between ZNF32 and autophagy in both xenograft tumors and in breast carcinoma patients." (PMID 25786368, 2015). "The relationship between ZNF32 and the pathological grade of breast cancer may be quite complicated inside organisms." (PMID 25786368, 2015). "Therefore, we speculate that ZNF32 H179A, H183A, H179, 183A can lead to formation of NSs in breast cancer cells." (PMID 40046230, 2025). "Altogether, we indicate that ZNF32 may be a potential target for breast cancer treatment." (PMID 25786368, 2015). "To examine the effects of ZNF32/GPER-regulated breast cancer cell stemness on tumour formation and tumour growth in vivo, we established stable knockdown of GPER expression in ZNF32 over-expressing ZR-75-30 cells." (PMID 30478301, 2018). "Collectively, our data reveal that ZNF32, via GPER/ERK signalling, is involved in breast cancer stemness and pro-survival effects in cancer cells." (PMID 30478301, 2018). "In this study, ZNF32 showed the ability to facilitate mammosphere formation and the expression of ALDH1, OCT4, Nanog and KLF4 in breast cancer cells." (PMID 30478301, 2018). "ZNF32 was shown to activate the AKT/mTOR pathway, which subsequently decreases the severe autophagic activity in breast carcinoma cells." (PMID 25786368, 2015). "We also compared the ZNF32 and LC3 II expression levels in the luminal A and luminal B subtype breast cancer samples." (PMID 25786368, 2015). "Because ZNF32 H179A and H183A promote the proliferation of breast cancer cells while ZNF32 H179, 183A does not, the protein structure analysis showed that the structures of H179, 183A, H179A, and H183A of ZNF32 were different." (PMID 40046230, 2025). "However, the role of ZNF32 and GPER in breast cancer stem cell-like properties and their functional significance have remained rather enigmatic." (PMID 30478301, 2018). "We conclude that ZNF32 can engage GPER/ERK signalling and confer breast cancer stem cell-like properties, which may indicate poor prognosis of breast cancer patients." (PMID 30478301, 2018). "Next, we measured ZNF32 and GPER expression in breast cancer tissues using IHC." (PMID 30478301, 2018). "These previously unrecognized observations suggest that high ZNF32/GPER expression may promote breast cancer malignant progression and therapy resistance by maintaining the properties of cancer stem-like cells in breast cancer." (PMID 30478301, 2018). "Using Taxol, a breast cancer clinical chemotherapy drug, we showed that GPER, along with ZNF32, is involved in drug sensitivity, as demonstrated by the results of knocking down or over-expressing ZNF32 or GPER." (PMID 30478301, 2018). "In addition, our results prove that ZNF32 and ALDH1 have the same expression trend in patient breast cancer tissues." (PMID 30478301, 2018). "Furthermore, correlations between ZNF32 and autophagy were observed in both MCF-7 xenograft tumors and in breast cancer patients." (PMID 25786368, 2015). "Furthermore, we compared the ZNF32 and LC3 II expression levels in two groups of patients with high and low pathological grades of breast cancer (Elston-Ellis modification of the Scarff-Bloom-Richardson Grading System)." (PMID 25786368, 2015).
breast carcinoma (continued). "However, it was shown that the ZNF32 and LC3 II expression levels are correlated in breast carcinoma patients." (PMID 25786368, 2015). "Both in vivo and in vitro experiments suggested that ZNF32 H179A and H183A but not H179, 183A could promote breast cancer cell proliferations." (PMID 40046230, 2025). "ZNF32 and GPER targeted therapies might provide new solutions for breast cancer treatment." (PMID 30478301, 2018). "Because of the similar functions of ZNF32 and GPER in breast cancer cell stemness regulation and since ZNF32 regulated GPER expression at the transcriptional level, we hypothesized that ZNF32 might affect the stem cell-like properties of the breast cancer cells through a GPER-dependent pathway." (PMID 30478301, 2018). "In the present study, we found that ZNF32 H179A, H183A, and H179, 183A could lead to NS formation in breast cancer cells, so we performed transcriptome sequencing and non-targeted metabolomics sequencing on WT and mutant breast cancer cells." (PMID 40046230, 2025).
colorectal cancer (2 papers, 2016 to 2022). A primary or metastatic malignant neoplasm that affects the colon or rectum. "Overexpression of ZNF32 in colorectal cancer (CRC) cells increased their self-renewal capacity." (PMID 35115495, 2022). "To clarify whether ZNF32 overexpression could promote resistance to another type of cancer cell, we detected the effect of ZNF32 on colorectal cancer cells." (PMID 27763636, 2016). "Overall, these findings suggest that ZNF32 might confer MDR to AC cells and colorectal cancer cells and protect them from drug-induced cell death." (PMID 27763636, 2016).
lung adenocarcinoma (2 papers, 2016 to 2022). A carcinoma that arises from the lung and is characterized by the presence of malignant glandular epithelial cells. "We previously demonstrated that in lung adenocarcinoma, ZNF32 contributes to the induction of multidrug resistance." (PMID 35115495, 2022). "Previously, we demonstrated that ZNF32 regulates the TGF-β receptor 2 signaling pathway in lung adenocarcinoma to confer multidrug resistance." (PMID 35115495, 2022). "We thus hypothesized that ZNF32 might enable the tolerance of cancer cells to anti-tumor drugs because higher ZNF32 expression has been found in cancer tissues and in drug-resistant lung adenocarcinoma (AC) cells." (PMID 27763636, 2016).
deafness (1 paper, 2016). An inherited or acquired condition characterized by the complete loss of the ability to hear from one or both ears. "Thus, ZNF32 can be used as a target gene for the treatment of deafness caused by hair cell damage in humans and other mammals." (PMID 27626680, 2016).
hepatocellular carcinoma (1 paper, 2015). A malignant tumor that arises from hepatocytes. "Taken together, our findings indicate a novel mechanism by which the Sp1-ZNF32-C1QBP axis protects against oxidative stress and implicate a promising strategy that ZNF32 inhibition combined with pro-oxidant anticancer agents for hepatocellular carcinoma treatment." (PMID 26497555, 2015). "ZNF32 downregulation promotes the apoptosis of hepatocellular carcinoma (HCC) cells exposed to the pro-oxidant agents, whereas ZNF32 overexpression protects against this effect." (PMID 26497555, 2015).
liver cancer (1 paper, 2020). An epithelial or non-epithelial malignant neoplasm that arises from the liver. "In liver cancer, the Zinc finger protein 32 (ZNF32) enhances the phosphorylation and activation of Src/FAK signaling, contributing to anoikis resistance." (PMID 33182556, 2020).
lung carcinoma (1 paper, 2016). "In addition, higher ZNF32 expression was found in lung cancer cells (A549 and PC9 cells) compared with primary lung epithelial cells NHBE." (PMID 27763636, 2016). "In vitro and in vivo experiments demonstrated that lung cancer cell proliferation is not affected by ZNF32." (PMID 27763636, 2016). "A novel therapy that combines both ZNF32 and TGF-β antagonists should be investigated through clinical trials with the aim of improving the efficiency of chemotherapy and prolonging the survival of patients with lung cancer." (PMID 27763636, 2016).